FOXO3 (forkhead box O3)
Diseases named in the same sentence as FOXO3 in open-access papers (continued):
Sharing a sentence is not in itself a finding about the gene and the disease.
tumor (continued). "Hence, these findings indicate that FOXO3 upregulation during the development of sorafenib resistance in HCC protects chemoresistant hepatocytes from the anti-tumor actions of sorafenib." (PMID 34769197, 2021). "SGPL1 knockout tumor tissue showed areas of low and high FOXO3 staining." (PMID 34073605, 2021). "Recent studies have revealed the association between FOXO3 and cellular apoptosis of tumor cells, which suggest that the further investigation of FOXO3-related apoptotic mechanisms in tumor cells will bring about a promising strategy on developing therapeutic alternatives." (PMID 33953834, 2021). "In contrast, when tumor cells form a glandular structure, cell-cell adhesion may contribute to resistance to FOXO3-induced growth suppression." (PMID 33795838, 2021). "As FOXO3 was confirmed to be upregulated by Met treatment, we speculated that FOXO3 plays a critical role in the anti-tumor effect of Met in HCC." (PMID 34546972, 2021). "StarBase revealed that miR-182-5p interacted with FOXO3, a well-known tumor suppressor gene." (PMID 33816238, 2021). "Moreover, the quiescent NSC FOXO3 transcriptional signature predicts similar tumor features as FOXO3 expression in GBM in the TCGA database." (PMID 36303712, 2021). "In vivo assays further verified that RBPJ-OE Mφ-Exos might inhibit tumor growth through a LBX1-AS1/miR-182-5p/FOXO3 pathway in xenograft tumor models." (PMID 33816238, 2021). "The expression of FOXO3 in OC tissues and tumor-adjacent tissues was detected by qRT-PCR and immunohistochemistry (IHC), respectively, with the results indicating that the expression of FOXO3 in OC tissues was markedly lower than that in the tumor-adjacent tissues." (PMID 34589270, 2021). "In addition, FOXO3 stimulates metastasis formation in other tumor entities, one of the biggest challenges in treating aggressive NB." (PMID 34572532, 2021). "This novel study demonstrated that an increased expression of FOXO3 may be an unfavorable clinical factor with diagnostic and prognostic value in HCC, being related to tumor development, poor OS and a high probability of invasion." (PMID 34771514, 2021). "miRNA‐96‐5p may exert a tumor promotion role through negatively regulating tumor suppressor gene FOXO3 and promoting cell proliferation." (PMID 32100957, 2020). "Additionally, hypoxia-induced miR-155 overexpression leads to enhanced resistance to radiotherapy via downregulating forkhead box O3 (FOXO3A), a tumor suppressor that when unphosphorylated induces apoptosis in tumor cells." (PMID 32316322, 2020). "The presence of the isoform-specific contributions of FoxO1 and FoxO3 to the tumor-inhibiting and life-extending effects of CR in mice warrants future studies using mice with myeloid-cell-lineage-specific deletion of the Foxo1 or Foxo3 gene under CR conditions." (PMID 32630045, 2020). "The tumour suppressor FOXO3 can antagonise the oncogenic activity of FOXM1 in a number of ways." (PMID 32372224, 2020). "The circRNA-FOXO3 may serve as a tumor suppressor in LC through sequestering miR-155 and enhancing FOXO3 expression." (PMID 32071550, 2020). "However, the other group found that the expression of circ-SMAD7 in EC was significantly down-regulated and negatively correlated with tumor stage and lymph node metastasis, and the low expression of circ-Foxo3 was related to poor prognosis." (PMID 32774156, 2020). "In accordance, we could demonstrate that nuclear FOXO3 promotes tumor angiogenesis in vivo and chemoprotection in vitro in aggressive NB." (PMID 31591479, 2020). "Moreover, this analysis showed that FOXO3 expression significantly associated with PERK-eIF2α pathway activation, as revealed by P-eIF2α, which is associated with tumour-infiltrating lymphocytes." (PMID 31312024, 2019).
tumor (continued). "On the one side, it is possible that hepatic activation of FOXO3 in patients sufficiently supports hepatocellular carcinogenesis, but on the other side it is also possible that FOXO3 activation is just a consequence and secondary-effect during tumor development." (PMID 31488102, 2019). "Down-regulation of FOXO3 promotes tumor metastasis in RCC 786O cells." (PMID 31540495, 2019). "In high-stage NB, FOXO3 promotes tumor angiogenesis in vivo and chemoprotection in vitro." (PMID 31861249, 2019). "Therefore, we propose that the FOXO3/CCND1 axis plays an essential role in LINC01355-mediated tumor suppression." (PMID 31243265, 2019). "Moreover, in colorectal cancer (CAC) patients with IBD background, RORγt-expressing tumor-infiltrating Treg cells sustain tumor growth in a transcription factor FoxO3-dependent manner." (PMID 31687412, 2019). "Importantly, ATP-content and resazurin salt reduction, which are both parameters for cell viability, demonstrated that S9 and S9OX preserved the viability of tumor spheres and strongly inhibited the apoptosis-inducing effect of FOXO3 in this 3D tumor model." (PMID 31789593, 2019). "Furthermore, FOXO3 upregulates the expression level of miR-30d, a kind of tumor-suppressive microRNAs, transcriptionally in RCC cell lines." (PMID 31540495, 2019). "miRNA-1 and miRNA-206 were demonstrated to target vascular endothelial growth factor A (VEGFA) and chemokine (C-C motif) ligand 2 (CCL2), while miRNA-31 was found to target forkhead box O3 (FOXO3a, a tumour suppressor) that was suggested to inhibit VEGFA expression in fibroblasts." (PMID 30944831, 2019). "Therefore, it is likely that FOXO3 exerts anti-tumor effects on EOC cells in part by inducing CCNG2 expression." (PMID 31013711, 2019). "Besides, circ-Foxo3 was found to down-regulated in patient tumor samples and in a group of cancer cells." (PMID 31533653, 2019). "Mechanistically, IL4Rα and IL13Rα1 could increase JAK2 signaling pathway and suppress tumor-suppressive activity of FOXO3." (PMID 31540495, 2019). "FOXO3 acts downstream of the phosphatidylinositol 3-kinase-protein kinase B (PI3K-PKB/AKT) signalling pathway as a tumour suppressor, preventing the transmission of potentially oncogenic mutations and activities by negatively controlling cellular proliferation." (PMID 31312024, 2019). "FOXO3 is one of the well-known tumor-suppressive transcriptional factors." (PMID 31540495, 2019). "In contrast, more and more studies described the tumor‐promoting actions of FOXO3." (PMID 30623608, 2019). "Blockage of the FOXO3 signaling axis could be a target for DCs-mediated enhanced anti-tumor immunity." (PMID 30658461, 2019). "Although FOXO3 is generally reported to suppress cell proliferation and tumorigenesis, recent studies support that FOXO3 may also sustain tumor cell growth and induce drug resistance." (PMID 30927552, 2019). "circ-Foxo3 induces tumor cell apoptosis by enhancing Foxo3 activity." (PMID 31324186, 2019). "FOXO3 was initially considered as a tumor suppressor that induces apoptosis and cell-cycle arrest." (PMID 31789593, 2019). "A reversible inhibition of FOXO3 activity by small compounds thereby might boost anti-tumor immune responses and limit side effects of FOXO3 functional inactivation." (PMID 31789593, 2019). "CircRNA-FOXO3 acts as a tumor suppressor through the miR-155/FOXO3 pathway." (PMID 30400981, 2018). "Continuous FOXO3 inactivation triggers cells to shift towards proliferation and survival, and can eventually drive tumorigenesis with the additional activation of oncogenes or inactivation of other tumour suppressors." (PMID 29180117, 2018). "By using ESCC mouse xenograft model, we found miR-10b-3p promotes multiple aspects of tumor development, including tumor growth and metastasis, and we verified the inversed correlation between miR-10b-3p and FOXO3 by IHC assays with the ESCC mouse xenograft model and human ESCC tissue samples." (PMID 30514328, 2018).
tumor (continued). "Pathway analysis suggests that miR-217 could be a potential oncogenic miRNA that negatively regulates the SIRT1, SMAD7, ROBO1, and FOXO3 genes, which are involved in tumor progression by diverse mechanisms." (PMID 30195786, 2018). "Additionally, nude mice injected with MDA-MB-231 cells overexpressing Foxo3, Foxo3P, or circ-Foxo3 have small tumor growth, demonstrating that Foxo3P or circ-Foxo3 has functional consequences similar to those of Foxo3." (PMID 30228872, 2018). "circ-FOXO3 could function as a sponge to bind several potential targeting miRNAs, resulting in increased gene expression and inhibition of tumor growth and angiogenesis." (PMID 29371930, 2017). "In our study, the data showed that RNAi directed against FOXO3 significantly increased the growth rate of tumor cells in a time-dependent manner, and the highest proliferation rates were 28.02±2.85 and 35.36±2.67% for siFOXO3-1 and siFOXO3-2, respectively, on day 8 (P<0.01)." (PMID 29072689, 2017). "In vivo analysis of nude mice subcutaneously injected with MDA-MB-231 cells transfected with circ-Foxo3 demonstrated that circ-Foxo3 could inhibit tumor growth." (PMID 28969099, 2017). "Interestingly, many of these genes are known to be involved in cell-cycle function (CDK2, CDK6, CCNB1, CEP55, CENPF), transcriptional regulation/tumor suppression (FOXO3, TOP2A), DNA-damage response (ASPM, XRCC4), and tumor progression (CYR61, MACC1, CXCR4)." (PMID 28482906, 2017). "Remarkably, a study has manifested that the overexpression of circ-Foxo3 (forkhead box O3) in MDA-MB-231 cells could restrain tumor growth in vivo as well as cancer cell proliferation and survival in vitro." (PMID 28928231, 2017). "Moreover, TUNEL staining of tumor sections revealed that circ-Foxo3 transfected tumor cells demonstrate extensive cell death, suggesting expansive cell apoptosis in the tumors." (PMID 28969099, 2017). "Consistent with their tumour suppressor functions, FOXO3 depletion by siRNA accelerated cell proliferation when compared with the control cells transfected with non-silencing control siRNA and empty vector, whereas BRCA1 overexpression suppressed the cell proliferation." (PMID 27043660, 2016). "The selection for survival might be due to genetic/epigenetic alterations of specific tumor cells and a specific, possibly hypoxic or nutrient-deprived micro-environment, which changes the physiologic outcome of FOXO3 activation." (PMID 27769056, 2016). "In the recently reported study by Yang W and colleagues, Foxo3 pseudogene (Foxo3P) could suppress tumor growth and angiogenesis by functioning as a sponge for microRNAs, and upregulate expression of the forkhead family of transcription factors, Foxo3." (PMID 27487124, 2016). "To study whether FOXO3 gene-dosage affects blood vessel growth into the tumor, we stained NB15/Ctr and NB15/FOXO3-derived tumors for the expression of the smooth muscle cell marker desmin to identify small vessels within the tumor tissue." (PMID 27769056, 2016). "Furthermore, NKPC tumors showed reduced expression of pERK, a diminished inactivation of Forkhead box transcription factor O (FOXO3), a tumor suppressor, and a decrease in the expression of oncomir-21, when compared with tumors in KPC mice." (PMID 27367029, 2016). "It suggests that FOXO3-activation in stage IV tumors after chemotherapy, as observed in patient biopsies, may support tumor-vascularization and/or vessel permeablility." (PMID 27769056, 2016). "We recently demonstrated that expression of circ- Foxo3 RNA could inhibit tumor cell cycle progression and promote cardiac senescence." (PMID 27713910, 2016). "As expected, the phosphorylated FOXO3 was exclusively located in cytoplasm of tumor cells." (PMID 27367029, 2016). "So how do our results relate to previous reports on FOXO3 as a tumor suppressor in NB?" (PMID 27769056, 2016).
tumor (continued). "Therefore, under hypoxic conditions, FOXO3 changes its function from a tumor suppressor to a growth-promoting transcription factor in those stage IV NB cells that already mainly rely on aerobic glycolysis as main energy source." (PMID 27769056, 2016). "Furthermore, tumour cells isolated from Eμ-myc and FoxO3−/−Eμ-myc mice had similar cell cycle profiles." (PMID 26764572, 2016). "Although FOXO3 is a tumor suppressor, we could find only one study that reported an association of FOXO3 genotype with all‐cancer mortality and another study in which a borderline association with cancer prevalence was found." (PMID 27071935, 2016). "In addition, the protein degradation mechanism, such as Ub-proteasome pathway, plays an essential role in regulating FOXO3 tumor suppressor function." (PMID 25823655, 2015). "FOXO3 is known as a tumor suppressor, and deregulation of FOXO3 is involved in various tumor types." (PMID 25823655, 2015). "AMPK tumor suppressor potential also acts through the Akt/FOXO3 signalling axis." (PMID 26798768, 2015). "Therefore, in the late stages of lung tumorigenesis, miR-182 expression was down regulated, compared with expression in the early stages, which led to tumor metastasis through, at least in part, an increase in FOXO3 expression." (PMID 24519909, 2014). "FOXO3 functions as a tumor suppressor in both ER+ and ER− BCs." (PMID 24416132, 2014). "Moreover, auranofin downregulates IκB kinase (IKK)-β and promotes nuclear localization and the activation of FOXO3 tumor suppressor, leading to cellular apoptosis in SKOV3 cells." (PMID 25096914, 2014). "As a transcriptional factor, FOXO3 is known to regulate various cellular processes such as cell cycle, cellular apoptosis, DNA damage repair, stress responses, metabolism, aging and tumor suppression in mammalian cells." (PMID 25096914, 2014). "In this study, we discovered tumor suppressor FOXO3 as the novel regulator of RRM2B." (PMID 24947616, 2014). "More recently it was shown that beside its function as a tumor-suppressor FOXO3 might also promote cancer cell survival." (PMID 23801966, 2013). "In addition, FoxO3 is a tumor suppressor and has been considered as a novel target for cancer therapeutics." (PMID 22489133, 2012). "Also, deletion of all FOXO1, FOXO3, and FOXO4 alleles in adult mice induced a cancer prone phenotype, supporting a tumour suppressing function of these proteins." (PMID 22848740, 2012). "Therefore, during tumor development, inhibition of FoxO3’s transcriptional activity promotes cell transformation, tumor progression, and angiogenesis." (PMID 22489133, 2012). "The modulation of FoxO3 stability and activity by methylation may be critical for fine-tuning cellular responses to stress stimuli, which may in turn affect FoxO3's ability to promote tumor suppression and longevity." (PMID 22820736, 2012). "A number of genes demonstrated reduced copy number and expression in KRAS mutant tumours, including putative tumour suppressor genes (FOXO3, EXTL2, PPP2R1B), negative regulators of the receptor tyrosine kinase oncogenic pathways (PTPRK, DGKZ, NCAM1), and negative regulators of Ras (EPHB2)." (PMID 21385341, 2011). "In addition to phosphorylation, the protein degradation mechanism plays a key role in regulating FOXO3 tumor suppressor function." (PMID 20625400, 2010). "As there are multiple FOXO family isoforms and FOXO3 and -4 were also inactivated in the c-MYC tumors, we could not exclude the possibility that other FOXOs compensated for the loss of Foxo1 tumor suppressor in the double-KO studies." (PMID 39325536, 2024). "In relation to therapy, overexpression of miR-155 seems to increase the chemoresistance of tumor cells to cisplatin, potentially by downregulating forkhead box O3 (FOXO3), a tumor suppressor transcription factor which could possibly be exploited for the treatment of drug-resistant CRC." (PMID 39767565, 2024).
tumor (continued). "However, a meta-analysis of the prognostic significance of FOXO3 in approximately 1000 HCC patients revealed positive associations between FOXO3 expression and tumor formation and invasiveness, as well as a negative association between expression and survival." (PMID 37174744, 2023). "Therefore, it is essential to further explore the regulation of FOXO3 on tumor cell pyroptosis." (PMID 35847844, 2022). "Additionally, FoxO3 exhibits tumor suppressive effects on GC, which might be a promising therapeutic target in clinic." (PMID 35342404, 2022). "Interestingly, several are suggested to have tumor suppressor roles (FOXO3, TRIM67, UHRF2, CHD6)." (PMID 36008825, 2022). "Moreover, it has been suggested that FOXO3 could participate in the autophagy-mediated modulation of sensitivity to chemotherapy in tumor cells." (PMID 34769197, 2021). "Considering all the previous evidence, which mostly defends a tumor-promoting action of the positive regulation of FOXO3, our meta-analysis certainly supports the findings reported by the majority of studies and underscores the role of FOXO3 overexpression on fostering HCC development." (PMID 34771514, 2021). "In other types of cancer, β-catenin may subvert the role of FOXO3 as a tumor suppressor." (PMID 34298659, 2021). "Therefore, to examine whether FOXO3 acts as a tumor suppressor or promoter in metastasis, the generation of a malignant model will be important." (PMID 33795838, 2021). "Thus, competitive binding of FOXO3 to β-catenin may switch CRC cells from Wnt-dependent proliferation to FOXO-mediated EMT, ultimately causing tumor cell dissemination." (PMID 34298659, 2021). "Thus, the inhibition of the phosphorylation of AKT by 6,8-diprenylorobol might contribute to the enhancement of the tumor-suppressive transcriptional activity of FOXO3 to block Huh-7 and HepG2 cell growth." (PMID 33312341, 2020). "Besides, FKBP5 could promote the interaction between AKT and PHLPP as a scaffolding protein and influence the phosphorylation of downstream FOXO3 as a tumor suppressor." (PMID 32760250, 2020). "To see whether hepatic activation of FOXO3 can sufficiently support hepatocellular carcinogenesis, or whether FOXO3 activation is just a secondary-effect during tumor development, we further generated a mouse model with hepatocyte-specific expression of a constitutively active form of FOXO3." (PMID 31488102, 2019). "However, the impact of FOXO3 on the metastatic potential of neuronal tumor cells remains largely unknown." (PMID 31861249, 2019). "FoxO3 may function as a trigger for apoptosis and is therefore known as a tumor suppressor." (PMID 30696075, 2019). "Similarly, forced expression of the pseudogene Foxo3P, Foxo3 circular RNA and Foxo3 mRNA all could suppress tumour growth and cancer cell proliferation and survival." (PMID 27561207, 2017). "Finally, we elucidated whether EnSCs exerted anti-tumor properties through affecting AKT/Forkhead box O3a (FoxO3a) axis in EOC cells." (PMID 27845405, 2016). "Therefore, we also analyzed whether there might be a selective process towards deletion of (ectopic) FOXO3 and stained the tumor sections also for FOXO3-expression." (PMID 27769056, 2016). "Our results provide additional rationale for combination mTOR/MEK inhibitor therapy because in addition to the anti-proliferative effects of MEK inhibitor treatment, mTOR inhibition resulting in enhanced PAK1/JNK/FOXO3-mediated apoptosis could inhibit tumor progression." (PMID 26121028, 2015). "Furthermore, this suggests a more complex and potentially cell type dependent mechanism of FOXO3 tumor suppression that may require multiple posttranslational modifications of FOXO3 for the various GPCR mediated effects." (PMID 25202904, 2014).